INS (insulin)
Diseases named in the same sentence as INS in open-access papers (continued):
Sharing a sentence is not in itself a finding about the gene and the disease.
type 2 diabetes (continued). "Type 2 diabetes (T2D) is defined by the World Health Organization (WHO) as a “metabolic disorder of multiple etiology characterized by chronic hyperglycemia with disturbance of carbohydrate, fat, and protein metabolism resulting from defects in insulin secretion, insulin action, or both”." (PMID 35406064, 2022). "Type II Diabetes Mellitus (T2DM) seems to be the most common metabolic disease worldwide, caused either by a defect in insulin secretion from pancreatic β-cells or the lack of responsiveness of insulin-sensitive tissues to the hormone." (PMID 35978298, 2022). "Standard self-monitoring was an essential means of achieving blood glucose goals for diabetic patients, which provided effective control of blood glucose and helped to improve glycosylated hemoglobin levels in people with type 2 diabetes who were not on insulin therapy." (PMID 35651857, 2022). "By contrast, combining the HFD and higher dose STZ leads to induction of later‐stage type 2 diabetes defined by frank hyperglycaemia, hypoinsulinaemia (but not insulin depletion) and severely impaired glucose tolerance, at the same time as retaining an obese phenotype." (PMID 35128667, 2022). "Further research is needed in type 2 diabetes patients treated with or without insulin." (PMID 36083989, 2022). "However, there is limited information on the clinical features and sequelae of people with type 2 diabetes (T2DM) not previously on insulin that require insulin as a new treatment when hospitalised with SARS-CoV-2 infection." (PMID 35256883, 2022). "Interestingly, the Bypass Angioplasty Revascularization Investigation in type 2 diabetes (BARI-2D) trial demonstrated a lower incidence of PAD in non-insulin than in insulin dependent patients." (PMID 36327256, 2022). "As BMI correlates with both type 2 diabetes and gestational diabetes, our use of a high BMI non-diabetic control group may have selected a relatively non-insulin resistant obese/overweight population." (PMID 35405936, 2022). "A declination in insulin secretion was observed with increased insulin demand over time due to progressive cell death and the majority of type 2 diabetes patients were not reliant on insulin when insulin secretion continued and insulin depletion seldom occurred." (PMID 36290804, 2022). "Any hypothesis of a direct effect of insulin on cancer incidence in type 2 diabetes should explain why there is no excess in patients with type 1 diabetes, who surely have an average longer use of insulin than do T2DM patients." (PMID 35681699, 2022). "Consistent with previous studies, high dietary fructose intake, as a low glycemic index sweetener, not merely has no adverse effects on insulin secretion stimulation but even it might be helpful for the management of type 2 diabetes." (PMID 33499915, 2021). "Subgroup analysis of changes (Δ) of anthropometric, performance and metabolic parameters based on response to changes in whole-body insulin sensitivity and PA participation over 5 years for patients with type 2 diabetes, divided into responders (n=17), Q2 (n=5), Q3 (n=23) and non-responders (n=30)." (PMID 34659107, 2021). "Thus, we immunized either non-insulin-resistant C57BL/6J mice or an insulin-resistant C57BL/6J mouse model of type 2 diabetes (T2D) with a single dose of BpOmpW." (PMID 34966388, 2021). "The absence of the first phase insulin response, a pathology that is typical of Type 2 diabetes, further exacerbates this latter issue, because this impairs the body's ability to prevent glucose being released from the liver when glucose is entering the circulation from dietary sources." (PMID 34336909, 2021). "In conclusion, the proteasome inhibitor PS-341 alleviates chronic low-grade inflammation while improving insulin sensitivity through upregulation of TM4 expression and may be a candidate for the treatment of metabolic inflammatory diseases, such as obesity and type 2 diabetes." (PMID 34074311, 2021).
type 2 diabetes (continued). "The role of ZBED6 in the pathophysiology of type 2 diabetes remains to be clarified, but it is tempting to speculate that ZBED6 maintains beta cell survival and proliferation at the cost of decreased insulin production, and that this is beneficial during long-term high-fat overfeeding." (PMID 34296320, 2021). "Type 2 diabetes is a result of the body’s lack of response to and/or production of insulin." (PMID 34490230, 2021). "Additionally, to define type 2 diabetes, no information was available on glycated hemoglobin (HbA1c) levels and medications such as diabetic pills or insulin injection status." (PMID 34086709, 2021). "We hypothesized that, like patients with neonatal diabetes, sulphonylureas might be able to promote incretin action with little or no direct effect on insulin secretion if used at a low enough dose in type 2 diabetes." (PMID 33693776, 2021). "Nutraceuticals that quell an increase in beta cell ROS production, that amplify or mimic autocrine insulin signaling, or that boost GLP-1 production, should help to maintain GSIS and suppress beta cell apoptosis in the face of glucolipotoxicity, postponing or preventing onset of type 2 diabetes." (PMID 35052168, 2021). "However, if insulin secretion and/or insulin sensitivity is not intact, hyperglucagonaemia is likely to aggravate the impaired glucose metabolism and finally lead to type 2 diabetes." (PMID 33275161, 2021). "However, the benefits of SMBG on glycemic control among those with type 2 diabetes (T2DM) not receiving insulin has remained inconclusive." (PMID 33441946, 2021). "Age 20–65 years, type 2 diabetes, diagnosis within 6 years, BMI 27–45, no insulin." (PMID 34631138, 2021). "Through meal replacement the daily insulin demand could be reduced by 40% in insulin-treated type-2-diabetes patients, while in noninsulin-treated type-2-diabetes patients fasting insulin levels reduced by more than half." (PMID 33922802, 2021). "In this real‐world study, although the hypoglycaemia rate was not high in adults with type 2 diabetes treated with insulin, there was a lower percentage of patients that achieved glycemic target among those reporting hypoglycaemia events vs patients who did not report them." (PMID 33532606, 2021). "In one study, relatives of individuals with type 2 diabetes had lower insulin sensitivity and those who did not respond to exercise training with increased insulin sensitivity also did not improve ATP production capacity and increased intrahepatic and intramuscular lipid concentrations." (PMID 34544430, 2021). "We show the usefulness of the model by simulating new and more challenging experimental setups in silico, e.g. the extracellular concentration of fatty acids during an insulin clamp, and the difference in such simulations between individuals with and without type 2 diabetes." (PMID 34972146, 2021). "Third, type 2 diabetes patients without using insulin were our study subjects." (PMID 33822810, 2021). "There’s a growing body of evidence that H2S plays an important role in type 2 diabetes, but its effect on insulin secretion and insulin target organs has not been consensus, which may be related to its concentration and production rate in the target organs." (PMID 34335475, 2021). "Patients with type 2 diabetes who required basal insulin therapy (IRR, 0.69; 95% CI, 0.63-0.75) or no insulin therapy (IRR, 0.36; 95% CI, 0.33-0.40) had a lower risk of hyperglycemic crises compared with those treated with bolus, with or without basal, insulin therapy." (PMID 34468753, 2021). "On the other hand, also a quantitative and qualitative improvement in muscle mass induced by exercise training may explain the enhancement in insulin sensitivity observed in subjects with obesity with or without type 2 diabetes that followed exercise programs." (PMID 33960110, 2021).
type 2 diabetes (continued). "Taken together, altered insulin-antagonistic responses, including the cortisol axis, glucagon and ANS, in obese insulin-resistant individuals may contribute to the development of long-term dysglycaemia and, hypothetically, also type 2 diabetes." (PMID 33241460, 2021). "In a further study, the prevalence of xerostomia among 120 elderly people diagnosed with type 2 diabetes (60 insulin-dependent individuals and 60 who did not require it) who had been undergoing treatment for at least one year using continuous medication was surveyed." (PMID 34190871, 2021). "Tending towards inhibition in response to the insulin treatment, and activation in response to the HF treatment, such a Ca2+-related mechanism might be critical in the onset of impaired granulosa cell function resulting from metabolic challenges especially in type 2 diabetes (T2D) patients." (PMID 34930403, 2021). "Glucose-induced insulin secretion is decreased and glucose tolerance is impaired in Trpm5−/− mice, while activation of TRPM5 may stimulate the pancreatic β-cells to secrete insulin, preventing the onset of diabetes mellitus type II." (PMID 33525598, 2021). "Thus, although we did not measure the serum insulin concentrations or insulin RI in the present study, insulin-induced retinal vasoreactivity can decrease under insulin-resistant states, such as type 2 diabetes." (PMID 34283877, 2021). "There are different mechanisms behind type 2 diabetes, for example, patients may not be able to produce enough insulin or not be able to utilize the existing insulin." (PMID 35011338, 2021). "The breakthrough discovery that plasma insulin concentrations were higher in maturity-onset diabetes compared to non-diabetic individuals after an oral glucose challenge, opened a long-lasting season of intense research into both the metabolic and molecular mechanisms underlying this phenomenon." (PMID 33555509, 2021). "GK rat is a non-insulin-dependent and non-obese spontaneous type II diabetic rat model." (PMID 34054555, 2021). "The achieved GIR during the hyperinsulinemic‐isoglycemic clamp method, is a direct measurement of insulin sensitivity, and the detected decrease in GIR could indicate a regression of insulin sensitivity in the individuals with type 2 diabetes, as a consequence of MR blockade." (PMID 34350730, 2021). "If the magnitude of these insulin pulses is reduced or absent there can be a defect in hepatic intracellular signaling resulting in increased hepatic output of glucose and reduced glucose utilization in animal models resulting in onset of Type 2 diabetes." (PMID 34458216, 2021). "In skeletal muscle, insulin inhibits proteolysis and increases the preference for BCAA oxidation, which may explain the blunted excursion of BCAA and BCKA metabolites in insulin-resistant individuals with type 2 diabetes as compared with NGT." (PMID 34131782, 2021). "Indeed, among patients with type 2 diabetes treated with bolus insulin, with or without basal insulin, the adjusted rate of DKA or HHS was 17.73 events per 1000 person-years." (PMID 34468753, 2021). "Additionally, miR-375 was found to be high in serum and pancreatic beta-cells of patients with type 2 diabetes mellitus (T2DM), which directly decreases the gene expression and secretion of insulin through targeting phosphoinositide-dependent kinase-1 (PDK1) and myotrophin, respectively." (PMID 33995938, 2021). "Furthermore, our previous data clearly shows that SIT could restore the elevations in blood glucose and serum insulin levels in the HFD and sucrose induced type 2 diabetic rats." (PMID 33917607, 2021). "• body weight and body composition did not change after 2 weeks of treatment• treatment with• either low-dose or high-dose r-metHuLeptin did not improve• liver, skeletal muscle, or adipose tissue insulin sensitivity• in weight stable, obese subjects with type 2 diabetes." (PMID 34084149, 2021).
type 2 diabetes (continued). "However, the molecular mechanism how insulin controls glucose transport across membranes and its relation to impaired glycemic control in type 2 diabetes remains not sufficiently understood." (PMID 32591906, 2020). "When comparing type 2 diabetes with MODY, the following variables were associated with MODY: lower age at diagnosis, BMI, HbA1c, and current age; having one diabetic parent; not being treated with insulin or oral antidiabetic agents; female sex." (PMID 32528556, 2020). "There have been no equivalent studies with insulin only in type 2 diabetes." (PMID 33134327, 2020). "Third, our study subjects were type 2 diabetes patients without using insulin." (PMID 32317650, 2020). "In the development of MS, the decrease of glucose-stimulated insulin secretion usually appears earlier and is more severe, whereas the baseline insulin secretion could not be impaired or even increase before the development of type 2 diabetes." (PMID 32617139, 2020). "However, the frequencies of effector CD4+ T cells, regulatory T cells, and B cells increased, suggesting a decrease of proinflammatory cellular immunity in nonpregnant type 2 diabetic patients treated with insulin, as compared to control subjects." (PMID 32626786, 2020). "In addition, in type 2 diabetes, there is an overall reduction in the insulin secretion rate, as the β-cells can no longer secrete sufficient insulin to maintain normal blood glucose levels." (PMID 32328034, 2020). "We also lacked information about diet, insulin, and oral hypoglycemic agents, and we could not distinguish between women with type 1 and type 2 diabetes." (PMID 33355674, 2020). "However, among subjects with type 2 diabetes (n = 1851), age at PHV did not significantly associate with insulin treatment (OR 1.06 per year decrease in age at PHV, 95% CI 0.97, 1.15)." (PMID 32201902, 2020). "Additionally, our results revealed that B. vernae extract or metformin treatment for 30 days significantly decreased (P < 0.01) serum FBG, INS, HOMA-IR, GSP, TNF-α, IL-1β, and IL-6 levels, whereas increased serum ISI levels (P < 0.01) in type 2 diabetic rats, compared with the model group." (PMID 32636751, 2020). "On the other hand, a tendency has been found between the change in insulin sensitivity parameter i.e., HOMA-S (r = 0.796, p = 0.069) in response to metformin treatment and the change in plasma vaspin concentration following conventional therapy for type 2 diabetes." (PMID 32917052, 2020). "We found that for patients with type 2 diabetes, it seems that the addition of sulfonylurea to insulin (whether basal only or basal plus bolus) did not increase the risk of hypoglycemia-related ED and hospital care beyond what was observed for insulin alone." (PMID 31922562, 2020). "Conversely, hyperglycemic hyperosmolarity syndrome (HHS) develops in patients with type 2 diabetes who still have some insulin secretory ability due to infection, non-compliance with treatment, drugs, and coexisting diseases, and is often accompanied by ketosis." (PMID 33292743, 2020). "Moreover, we have recently conducted another study on nonpregnant person with type 2 diabetes on insulin treatment." (PMID 32626786, 2020). "Importantly, there is accumulating evidence to suggest that mitochondrial dysfunction in the pancreatic beta cell leads to impaired glucose-stimulated insulin secretion (GSIS) and may contribute to the development of type 2 diabetes." (PMID 32350566, 2020). "In case of people with Type 2 Diabetes or insulin-treated Type 1 Diabetes, physical exercise fails to sufficiently reduce insulin level in the blood and as a result the glycogen breakdown in the liver may not be sufficient to meet the additional glucose needs." (PMID 32155149, 2020).
type 2 diabetes (continued). "Current frontline therapies for patients with type 2 diabetes include glucagon-like peptide-1 (GLP-1) mimetics that not only harness the insulin-stimulating and glucagonostatic properties of the endogenous hormone, but also lower body weight through induction of satiety." (PMID 32141504, 2020). "Also, oral dose of encapsulated glutamine did not stimulate consistent increase in GLP-1 and insulin secretion in type 2 diabetes patients." (PMID 32983244, 2020). "Because there has been no quality improvement initiatives targeting patients with type 2 diabetes (T2D) receiving basal insulin therapy, this study evaluated the effectiveness of physician‐targeted education for optimizing glycemic management in these patients in China." (PMID 31222955, 2020). "Type 2 diabetes (T2D) is a classic example of chronic metabolic disorder which is characterised by consistently high levels of blood glucose, mainly due to lack of sensitivity to insulin and often combined with some degree of pancreatic β-cell dysfunction." (PMID 32325761, 2020). "This retrospective analysis of 139 patients with type 2 diabetes switched from prior anti-hyperglycemic therapy to basal-bolus insulin therapy with V-Go showed a significant and clinically relevant 1.52% reduction in A1C using a lower TDD of insulin after a mean of 5 months of therapy." (PMID 33202616, 2020). "Thus, the objective of this study was to evaluate the change in A1C and insulin total daily dose (TDD) in a suboptimally-controlled (not achieving A1C target of ≤ 7%) type 2 diabetes population after switching to V-Go." (PMID 33202616, 2020). "The aim of this study was to investigate the effect of metformin in combination with insulin on cardiovascular autonomic neuropathy (CAN) and distal peripheral neuropathy (DPN) in individuals with type 2 diabetes (T2DM)." (PMID 32979921, 2020). "The pathophysiology of EPI in type 1 and type 2 diabetes is not fully clear but includes inflammation, fibrosis, and steatosis of the exocrine pancreas and disturbances in the islet-acinar axis especially decreased trophic effects of insulin." (PMID 32239341, 2020). "Estimates of post-load glucose, ISI and HOMA-IR, did not include insulin users, which may have led to an underestimation of the observed findings in more severe type 2 diabetes." (PMID 32757152, 2020). "With regard to type 2 diabetes, AVP may directly stimulate metabolism including hepatic glucose production or insulin release from the pancreas and may adversely affect whole-body responses to insulin." (PMID 32210168, 2020). "Metabolic syndrome (MS) and type-2 diabetes mellitus (T2DM) are chronic metabolic disorders and prevalent diseases adversely impacting health worldwide, which are characterized by increased levels of circulating glucose, insulin, atherogenic lipoprotein subfractions, and inflammatory cytokines." (PMID 31936892, 2020). "Short-term toxicity within the first 15 days was not unexpected, essentially related to pre-existing type 2 diabetes exacerbations in 29 of 108 patients (26.9%), with oral anti-diabetic drugs alone required in 10 patients (34.5%), and insulin therapy in 19 patients (65.5%)." (PMID 33326457, 2020). "While hypertension and albuminuria were effect modifiers, our finding showed among individuals without hypertension and albuminuria, C-peptide level is a reliable marker for the prediction of type 2 diabetes independent of glucose and insulin which are predictors of type 2 diabetes as well." (PMID 32957570, 2020). "Therefore, we cannot rule out the existence of insulin resistance in these adipocytes, similar to the changes in adipose tissues in type 2 diabetes patients." (PMID 31989870, 2020). "Patients with type 2 diabetes are not dependent on exogenous insulin, although some of them may require it to control their condition." (PMID 33100218, 2020).